VPS26B (VPS26 retromer complex component B)
Description:
Acts as a component of the retromer cargo-selective complex (CSC). The CSC is believed to be the core functional component of retromer or respective retromer complex variants acting to prevent missorting of selected transmembrane cargo proteins into the lysosomal degradation pathway. The recruitment of the CSC to the endosomal membrane involves RAB7A and SNX3. The SNX-BAR retromer mediates retrograde transport of cargo proteins from endosomes to the trans-Golgi network (TGN) and is involved in endosome-to-plasma membrane transport for cargo protein recycling. The SNX3-retromer mediates the retrograde transport of WLS distinct from the SNX-BAR retromer pathway. The SNX27-retromer is believed to be involved in endosome-to-plasma membrane trafficking and recycling of a broad spectrum of cargo proteins. The CSC seems to act as recruitment hub for other proteins, such as the WASH complex and TBC1D5. May be involved in retrograde transport of SORT1 but not of IGF2R. Acts redundantly with VSP26A in SNX-27 mediated endocytic recycling of SLC2A1/GLUT1 (By similarity).
Synonyms: MGC10485; Pep8b
Tractability: Antibody: UniProt places it where antibodies can reach, with medium confidence. PROTAC: ubiquitination databases record sites on it; its protein half-life has been measured.
Gene: Protein-coding gene on chromosome 11 (134,224,613 to 134,247,794, forward strand). Ensembl gene ENSG00000151502.
Subcellular location: Cytoplasm; Membrane; Early endosome; Late endosome
Gene Ontology:
Molecular function: protein binding
Biological process: endocytic recycling; intracellular protein transport; regulation of macroautophagy; retrograde transport, endosome to Golgi; regulation of neurotransmitter receptor localization to postsynaptic specialization membrane
Cellular component: cytoplasm; early endosome; endosome membrane; late endosome; retromer complex; retromer, cargo-selective complex; cytosol; glutamatergic synapse; membrane; phagocytic vesicle; postsynaptic early endosome; postsynaptic recycling endosome
Genetic constraint (gnomAD): Loss-of-function variants: 10 observed, 34.85 expected, observed/expected ratio (o/e) 0.29, 90% interval 0.18 to 0.49. The upper end of that interval is the gene's LOEUF score, 0.49, which puts it in group 2 of 6, group 1 being the genes least tolerant of losing a copy. Missense variants: 317 observed, 474.1 expected, observed/expected ratio (o/e) 0.67, 90% interval 0.61 to 0.73. Synonymous variants: 190 observed, 187.79 expected, observed/expected ratio (o/e) 1.01, 90% interval 0.9 to 1.14.
Homologues: Orthologues: guinea pig VPS26B (99% identical), mouse Vps26b (99% identical), rat Vps26b (99% identical), dog VPS26B (98% identical), macaque VPS26B (98% identical), pig VPS26B (98% identical), chimpanzee VPS26B (97% identical), rabbit VPS26B (97% identical), tropical clawed frog vps26b (89% identical), zebrafish vps26bl (88% identical), zebrafish vps26b (84% identical), Drosophila melanogaster Vps26 (68% identical), and 1 more. Paralogues in human: VPS26A (68% identical), VPS26C (20% identical).
Diseases named in the same sentence as VPS26B in open-access papers:
VPS26B is named in the same sentence as 7 diseases in open-access papers, as found by Europe PMC text mining. Sharing a sentence is not in itself a finding about the gene and the disease. The quoted sentences say what the papers report.
multiple system atrophy (1 paper, 2016). Multiple system atrophy (MSA) is a neurodegenerative disorder characterized by autonomic failure (cardiovascular and/or urinary), parkinsonism, cerebellar impairment and corticospinal signs with a median survival of 6-9 years. "Genetic screening on the whole VPS26a, VPS26b, and VPS29 genes have identified other VPS mutations which may produce pathogenic effects both in PD and atypical parkinsonisms, such as PSP (Progressive Supranuclear Palsy), MSA (Multiple system atrophy), and Lewy body dementia (LBD)." (PMID 27932943, 2016).
sarcoma (1 paper, 2021). A usually aggressive malignant neoplasm of the soft tissue or bone. "Significantly, the APA event of VPS26B was determined as an overlapping independent prognostic biomarker for sarcoma patients." (PMID 34195183, 2021).
cancer (1 paper, 2021). A tumor composed of atypical neoplastic, often pleomorphic cells that invade other tissues. "Nevertheless, few studies reported the role of VPS26B or related regulation in cancers." (PMID 34195183, 2021).
VPS26B also shares sentences with these, for which no sentence is quoted: Alzheimer disease (1 paper); Obesity (1); tumor (1); viral infections (1).